CCR6 (C-C motif chemokine receptor 6)
Diseases named in the same sentence as CCR6 in open-access papers (continued):
Sharing a sentence is not in itself a finding about the gene and the disease.
tumor (continued). "However, the same cells increased the recruitment of neutrophils through interleukin 8 (IL-8) secretion and attracted cytotoxic CCR5+CCR6+CD8+T cells into tumor tissue through CCL5 and CCL20 production." (PMID 37185750, 2023). "In relation to the histopathological type, a slightly higher expression level of CCR6 mRNA was observed in tumor tissue of AC patients compared to control tissue (median RQ: 8.778 and 8.756, respectively) but the differences were statistically insignificant (p > 0.05, Mann–Whitney U-test)." (PMID 37316552, 2023). "CCR6+ populations are also found accumulating in new lymph structures around the tumour." (PMID 35557940, 2022). "Indeed, under cisplatin treatment, there is a production of CCL20 and IL-1β by murine lung and breast cancer cells, which triggers the recruitment of the CCR6+ type 3 innate lymphoid cells (ILC3) at the tumor site." (PMID 36429101, 2022). "CCR6 is a specific receptor for CCL20, and CCR6 expression has also been shown on tumor cells." (PMID 36045408, 2022). "Moreover, EPS-R1 skewed intratumoral CCR6+ CD8+ T cells toward an IFN-γ-producing CD8+ T cell population that inflamed the tumor tissues." (PMID 36726985, 2022). "This analysis showed, in tumor samples, an increased percentage of CCR6+ CD8+ T cells expressing both CCR5 and CXCR3 (p < 0.01) and a decrease of Th17 and Tc17 cells expressing only CCR5 (p < 0.01 and p < 0.0001, respectively) and an increase of Tc17 cells expressing only CXCR3 (p < 0.0001)." (PMID 36551555, 2022). "In addition, a study with 84 patients of LUAD showed that higher expression of CCR6 in tumor was an independent predictor of a better prognosis in LUAD." (PMID 36612054, 2022). "The effects of CCR6 on tumor progression and prognosis were controversial." (PMID 36612054, 2022). "Researchers have found that docetaxel could rescue immunity functions against tumor cells by reducing their secretion of CCL20 interacted with CCR6+ Tregs." (PMID 35497874, 2022). "The AKT/NF-κB pathway played an important role in CCR6-mediated tumor angiogenesis." (PMID 36286020, 2022). "CCL20 produced in the tumor microenvironment may also selectively attract Th17 cells expressing high levels of CCR6." (PMID 36107259, 2022). "In addition, the RORγt agonist promoted Type 17 T cell migration by upregulating CCL20 and CCR6 expression, and Type 17 T cell tumor infiltration." (PMID 35459193, 2022). "CCR6+ Tregs are enriched in human solid tumors such as NSCLC, HNSCC, laryngeal and esophageal SCC and chemotherapy-resistant CRC compared to NAT and PBMC and are associated with tumor progression." (PMID 33924428, 2021). "Altogether, these results argue in favor of a CCR6 blockade to inhibit tumor progression." (PMID 33924428, 2021). "Upregulation of CCR6 on immune cells may therefore be the more prudent therapeutic approach for enhancing T cell infiltration while maintaining tumor control." (PMID 34771532, 2021). "Interestingly, after 17 days, Ccr6+/+ → Ccr6–/– mice presented with a significantly lower tumour growth and vascularisation of the tumour than tumours grown in Ccr6+/+ → Ccr6+/+ control mice." (PMID 32601464, 2020). "In addition, IL-9 boosted the production of CCL20 in lung tissue, leading to the recruitment of CCR6+ DCs and CCR6+ CD8+ T cells to the tumor bed." (PMID 32508847, 2020). "Given that the vasculature plays a major role in regulating tumour growth as well as metastasis, we investigated whether microvascular endothelial cells express CCR6, the corresponding receptor for CCL20, on their surface." (PMID 32601464, 2020). "The fact that CCR6-positive vessels are closely apposed to CCL20-expressing tumours allowed us to hypothesise that CCL20 might be able to functionally activate the microvasculature and induce angiogenesis." (PMID 32601464, 2020). "Specifically, blocking the activity of CCR6 in the microenvironment of the tumour might inhibit tumour neoangiogenesis and thereby enhance conventional antitumour therapies." (PMID 32601464, 2020).
tumor (continued). "In contrast, B16F10 tumours grown in Ccr6-deficient mice displayed dramatically reduced numbers of tumour-infiltrating vessels, and were notable for their lack of a macrovasculature." (PMID 32601464, 2020). "Furthermore, CCL19/CCR7, CXCL12/CXCR4, and CCL20/CCR6 were shown to be potential new targets for tumor gene therapy in type 2 PRCC." (PMID 32775427, 2020). "Moreover, BrCa cells secrete CCL20, which recruits CCR6 expressing immune cells in the tumor vicinity." (PMID 30850664, 2019). "CCR6+ ILC3s cells were shown to possess anti-tumor functions in certain contexts." (PMID 31024531, 2019). "However, although expression of Ccl5 and its receptors Ccr1 and Ccr3 were not affected by IL-6Rα deficiency in CAC, expression levels of Ccl20 and of its unique receptor Ccr6 were reduced in knockout tumours." (PMID 29695802, 2018). "Furthermore, the same group of researchers introduced a dual anti-cancer mechanism by modulating the CCR6/CCL20 axis in a tumor environment." (PMID 30453514, 2018). "However, CCL20 administration in CCR6+ tumor bearing mice increased tumor weight and numbers of spontaneous lung metastases suggesting the potential involvement of CCR6 in lung metastasis formation." (PMID 30420855, 2018). "CCR6 play an important role in the regulation of tumor cell proliferation, invasion and migration." (PMID 29383156, 2017). "Notably, the majority of tumor-infiltrating dendritic cells were CCR6-positive, consistent with previous findings." (PMID 26047945, 2015). "However, accumulating recent findings show that the CCR6 on Th17 cells also plays a critical role in tumor development." (PMID 25768730, 2015). "CCR6 was positively expressed in 44.7% (51/114) of tumor tissues." (PMID 26634210, 2015). "We then sought to examine whether CCR6 influenced early hyperplasia of mammary glands during tumor initiation as well as late stage tumorigenesis." (PMID 26047945, 2015). "However, the identification of tumor-metastasis-related genes regulated by the CCR6/CCL20 axis will be clinically important for designing targeted therapies for the treatment of CRC in the future." (PMID 24979261, 2014). "The percentage of rectal epithelial cells co-expressing CCL20 and CCR6 was 20.4% of all the patients, including 23.4% (18/77) of patients without neoplasia and 6.3% (1/16) of patients with UC-associated neoplasia." (PMID 24179507, 2013). "A positive feedback cycle may be formed in the tissue environment: CCR6+ memory TH17 is homed to tumor site by high levels of CCL20." (PMID 23316374, 2012). "However, other chemokine receptors, for example, CXCR3, and CCR6, which are shared with memory Th1, Th2 and Th17 cells, have also been shown to be expressed by tumor-infiltrating Treg-cells." (PMID 21559338, 2011). "To elucidate whether local prior proliferation of CCR6+Tregs contributed to their accumulation in tumor mass, we treated 4T1 bearing mice with vinblastine (a cell cycle inhibitor)." (PMID 21655250, 2011). "The association of CCR6 expression in tumor cells with shorter RFS in univariate analysis did not remain statistically significant in the multivariate analysis." (PMID 21624121, 2011). "However, recently, accumulating finding show that the CCR6 expression on Tregs also plays a critical role in tumor development." (PMID 21935436, 2011). "Consistently, we found tumor-infiltrating Treg-cells almost exclusively expressed CCR6." (PMID 21559338, 2011). "It was shown that tumor-resident DCs significantly stimulated the proliferation of CCR6+ Tregs in vitro in a time and dose dependent manner (p<0.05), while no such effect was observed for any of the other APCs isolated from tumor mass (p>0.05)." (PMID 21655250, 2011). "Combing these data suggested that CCR6+Tregs might play a critical role in immunosuppression of anti-tumor immunity." (PMID 21655250, 2011). "It is worth noting that the Tregs in tumor environment expressed low to even undetectable CCR6." (PMID 21935436, 2011).
tumor (continued). "We infer this may result from the strong expression of CCL20 in tumor environment, which inversely internalizes the CCR6 expression like CCR4." (PMID 21935436, 2011). "In addition, the high levels of expression of CCR6 in the Tc17 cells from PBMCs also indicate that these cells were able to migrate to tumor tissue." (PMID 22051182, 2011). "We sought to characterize the role of the CCL20/CCR6/IL-17 axis in NSCLC tumor growth." (PMID 21949768, 2011). "Importantly, the proportion of CCR6+Tregs in tumor mass in vinblastine treated groups also decreased significantly compared with control group (p<0.05)." (PMID 21655250, 2011). "On the other hand, the functional character of tumor-resident APC might also be critical for the different proliferation of CCR6+Tregs and CCR6−Tregs in vivo." (PMID 21655250, 2011). "In addition, there wasn't any change in the frequency of CCR6+Tregs or CCR6−Tregs in PBMCs during tumor progression." (PMID 21655250, 2011). "Moreover, CCR6+Treg frequency at late stage of tumor in TILs was higher than that in DLNs; In contrast, frequency of CCR6− Tregs in TILs at late stage was similar to that in DLNs (p>0.05)." (PMID 21655250, 2011). "Consistent with this concept, our data demonstrated that naïve Treg-cells derived from FoxP3GFP mice do not express CCR6, while FoxP3GFP+ Treg-cells predominantly expressed high levels of CCR6 in tumor tissue 2 weeks after adoptive transfer into tumor bearing mice." (PMID 21559338, 2011). "Our data provide strong evidence that these CCR6+ Treg-cells exhibit a prevalent memory phenotype, and clearly they might be tumor antigen experienced." (PMID 21559338, 2011). "We next tried to elucidate whether selective enrichment of CCR6+ Tregs in the tumor mass was related to their preferable recruitment or their prior in site proliferation." (PMID 21655250, 2011). "Take together, this data suggest that CCL20/CCR6 interactions in the tumor microenvironment may stimulate NSCLC disease progression." (PMID 21949768, 2011). "CCR6 may increase tumor cells' motility and therefore their metastatic potential by acting on the cytoskeleton, as has been described in a model of colonic epithelium." (PMID 21624121, 2011). "Furthermore, a close association was observed between MIP-3α-producing tumour cells and immature CCR6+ DC recruitment to the tumour bed." (PMID 20969772, 2010). "Hence, we incubated the tumour cells with a CCR6 blocking antibody 30 min before the incubation of the migration assay." (PMID 20877351, 2010). "The majority of tumor samples that expressed CCL20 co-expressed CCR6." (PMID 19340288, 2009). "The potential to inhibit tumour growth by targeting VLCs is illustrated by our studies with CCR6-immunotoxins: Tumours injected in the presence of anti-CCR6 antibodies bound to saporin, a ribosomal-inactivating protein, grew 2.6-fold less than tumours injected with an isotype control antibody." (PMID 15785750, 2005). "Notably, CCL20 and its receptor CCR6 are important in tumor microenvironment interactions." (PMID 39985603, 2025). "Furthermore, tumor growth was most inefficient in CCR6-/- knockout mice." (PMID 38730689, 2024). "Next, we asked if CDKN2A alteration could affect other immune components; therefore, we checked the correlation of CDKN2A alteration with the chemokine CCL4 and the chemokine receptor CCR6, which are known for their immunosuppressive roles against tumor development." (PMID 37626750, 2023). "In addition, activation of the AKT/NF-κB pathway might be involved in CCR6-mediated tumor angiogenesis, thereby promoting the secretion of VEGFA." (PMID 36286020, 2022). "Moreover, CCL20 and CCR6 comprise a chemokine regulatory axis to regulate the behavior of cancer cells and immune cells concurrently, thereby shaping tumor immune microenvironment (TIME) states and influencing the combat between the immune system and the tumor." (PMID 35864953, 2022).
tumor (continued). "Notably, inhibition of miR-21 expression significantly decreased the proliferation of C-C Motif Chemokine Receptor 6 (CCR6+) Tregs, altered the recruitment of CCR6+ Tregs into the tumor site and effectively endowed CD8+ T cells with an anticancer function by altering the PTEN/Akt axis." (PMID 36189271, 2022). "Additionally, Th1 cell-derived IFN-γ induces enhanced production of tumorotoxic nitric oxide and TNF-α in tumor-infiltrated macrophages while Th17 cell-sourced IL-17 stimulate production of CXCL16 in tumor DCs, enabling increased recruitment of tumoricidal CCR6-expressing CD8+CTLs." (PMID 35757015, 2022). "Given the CCL20/CCR6 axis plays a critical role in inflammatory diseases 32, we speculate that high CCL20 expression may be associated with the locally active inflammatory state of the tumor, which enhances the pyroptosis marker expression." (PMID 35864953, 2022). "Thus, the CCL20/CCR6 axis is involved in the development of inflammatory diseases and tumor angiogenesis, but its role remains unknown in vascular disorders, including SSc vasculopathy." (PMID 34774095, 2021). "Thus, CCR6 may be primarily involved in the recruitment of Th17 cells and Treg cells into tumor tissues." (PMID 34885241, 2021). "Furthermore, we found that vessels in the vicinity of CCL20-positive tumour tissues expressed CCR6." (PMID 32601464, 2020). "Since the administration of Th17 cells in CCR6-deficient mice did not inhibit tumor growth, the authors hypothesized that CCR6 is required for the response to Th17 therapy." (PMID 32121394, 2020). "However, recent reports showed that CCL20-CCR6 is part of a NF-κB/chemokine onco-immuno crosstalk that leads to CCR6 dependent immune cell recruitment, which in turn promotes tumor cell invasion, proliferation and resistance against cell death inducing treatments." (PMID 31561620, 2019). "Moreover, Ccl20 and Ccr6 increased in obese control tumours and were downregulated in non-tumour tissue and tumours of obese IL-6Rα-deficient mice." (PMID 29695802, 2018). "MMTV-PyMT cancer cell transplant experiments showed that tumor growth in a CCR6-null microenvironment was significantly inhibited compared to wild-type microenvironment conditions, directly demonstrating that the mammary stroma is dependent upon CCR6 for adequate tumor initiation and growth support." (PMID 26047945, 2015). "Finally, the size of tumor mass in CCR6+Tregs co-transferred mice was significantly elevated compared with that in CD8+T cells transferred group and CCR6−Tregs co-transferred group, while it decreased obviously in vinblastine pre-treated CCR6+ Tregs co-transferred group(p<0.05)." (PMID 21655250, 2011). "Finally, the possible role of tumor resident DCs in the proliferation of CCR6+ Tregs was studied." (PMID 21655250, 2011). "Our finding suggested that CCR6+ Tregs, a distinct subset of Tregs, exert its predominant suppressive role in tumor immunity through prior in situ expansion, which might ultimately provide helpful thoughts for the designing of Treg-based immunotherapy for tumor in the future." (PMID 21655250, 2011). "Therefore, the different proliferation of CCR6+Tregs and CCR6−Tregs in tumor mass might be partly attributed to their different sensitivity following interaction with intra-tumoral DCs." (PMID 21655250, 2011). "However, cultured supernatant of 4T1 tumor cells attracted similar counts of CCR6+ and CCR6−Tregs." (PMID 21655250, 2011). "Next we tried to find whether tumor-resident APCs could promote the proliferation of CCR6+ Tregs." (PMID 21655250, 2011). "In addition, tumour cells and tubulus cells of normal kidney demonstrated weak expression for CCR6." (PMID 20969772, 2010). "Tumor cells, along with other stromal and immune cells in the TME, secrete chemokines including CCL22, CCL20, and CXCL12, which bind to CCR4, CCR6, and CXCR4 on Tregs and direct their recruitment and activation within the TME." (PMID 41890756, 2026).
tumor (continued). "Enhanced expression of the CCL20 chemokine, the ligand of CCR6, was observed in cancer tissue compared to the normal condition, along with an increased CCL20 gradient in mouse tumor-draining LNs." (PMID 42093985, 2026). "We found that the proportion of tumor‐infiltrating CD4+CD25+Foxp3+ Tregs, especially the CCR6+ Treg subpopulation, was attenuated." (PMID 39853961, 2025). "Both the co-expression and single expression of CXCR5 or CCR6 in HER2-CAR T cells resulted in a markedly higher positive staining for CD4 + and CD8 + CAR T cells in the tumor tissue compared to those in the HER2-CAR T cell and Control-T treatment groups." (PMID 40764989, 2025). "Gal1‐induced TAMs recruited CD4+CD25+Foxp3+CCR6+ Tregs through the CCL20‐CCR6 axis and culminated in impaired anti‐tumor immune responses in HCC." (PMID 39853961, 2025). "In contrast, administering CCL20 via intratumoral injection in subcutaneous HCC mouse models restored tumor growth, reduced the CD8+ T cell infiltration, increased the frequency of CD4+CD25+Foxp3+ Tregs and CCR6+ Tregs in shGal1 tumors." (PMID 39853961, 2025). "The chemokine receptor CCR6, and its ligand CCL20 have been described to play a role in tumor progression in several cancers." (PMID 39825956, 2025). "In this study, we demonstrated that miR-183-5p derived from HCC cell-derived EVs induces endothelial cell angiogenesis, facilitating crosstalk between tumor and endothelial cells through the CCL20/CCR6 axis, thereby promoting HCC progression." (PMID 40115013, 2025). "Key chemokine receptors, such as CCR2, CCR6, CCL20 and CXCR4, have been identified as pivotal contributors to Treg recruitment at tumor sites." (PMID 41445742, 2025). "CCR6 is expressed in melanoma cells, in vivo addition of CCL20 leads to tumor growth and progression." (PMID 39825956, 2025). "mDCs recruitment into the TME has been reported to depend on the CCR6/CCL20 axis, the latter of which showed a significant increase of expression in tumor tissues (logFC=3.5)." (PMID 40552117, 2025). "The HER2-CXCR5-CCR6-CAR T group demonstrated the most effective control over orthotopic HCC827-Luciferase tumors, with a final tumor bioluminescence photon flux of 14,600 ± 5,313.67 p/s, highlighting the synergistic benefits of CXCR5 and CCR6 co-expression." (PMID 40764989, 2025). "CCL20, a ligand for CCR6, draws CCR6-expressing Tregs to the TME, driving tumor growth and worsening patient prognosis." (PMID 41445742, 2025). "For example, HER2‐targeting CAR–MAIT cells infiltrate tumor tissues by expressing high levels of homing receptors, such as CXCR6 and CCR6, in breast cancer models." (PMID 41179703, 2025). "Th17 cells can be recruited to the tumor sites by the expression of CCR6 and binding to its natural ligand CCL20 highly expressed on tumor tissues, which is coordinated by long non-coding RNA (lncRNA-u50535)." (PMID 40963621, 2025). "HCC‐mediated CCL20 production has been shown to recruit CCR6+CD5+ B cells, promoting angiogenesis and thus facilitating tumour growth." (PMID 40913253, 2025). "In syngeneic tumor-bearing mice, CCL20/CCR6 distortion rejuvenated T cell activity and prolonged the survival of tumor-bearing mice." (PMID 39985603, 2025). "An EPS from lactobacilli strains has been reported to increase CCR6+ CD8+ T-cell populations in Peyer’s patches, supporting their migration to CCL20-expressing tumor sites and thereby boosting the effects of immune checkpoint blockades (e.g., anti-CTLA-4 mAb)." (PMID 41301527, 2025). "In the H group, there were also a few specific interactions, such as the interactions between the dendritic cell-expressed ligands CCR6 and CXCR3 with the tumor cells-expressed receptor CCL20." (PMID 39268081, 2024). "Consistent with this, both CCR6 and CCL20 exhibited significant upregulation in tumor tissues compared to their matched normal counterparts in LUAD patients." (PMID 38551001, 2024).